ITGA4 (integrin subunit alpha 4)
Diseases named in the same sentence as ITGA4 in open-access papers (continued):
Sharing a sentence is not in itself a finding about the gene and the disease.
breast carcinoma (8 papers, 2015 to 2025). "We demonstrate that DPT-CTC clusters drive breast cancer metastasis via VLA-4 (ITGA4/B1)–VCAM1 interactions." (PMID 40955669, 2025). "In the case of ITGA4 in breast cancer, we witness the opposite situation, where the fraction of HER2 positive tumors is significantly enriched with samples harboring ITGA4 methylation." (PMID 33500458, 2021). "To provide a mechanistic explanation of the inhibitory activities of Flavipin on breast cancer cells, we examined selected anti-apoptotic (Bcl2), adhesion (ITGA4) and pro-metastatic (Sox4) markers." (PMID 27907195, 2016). "In a recent study of microarray-based methylated-CpG island recovery assay, hypermethylation and low expression level of ITGA4 were reported to be enriched in breast cancers." (PMID 26121976, 2015). "ITGA4 acquires expression in a subset of breast carcinomas, and methylation of its promoter may be preventive against expression in some tumors." (PMID 33500458, 2021). "Therefore, the suppressive effects of Flavipin on Bcl2 and ITGA4 in the examined breast cancer cells could be among the reasons that contributed to the inhibited migration." (PMID 27907195, 2016). "In this study, we have identified high frequencies of cancer specific abnormal hypermethylation of the parts of promoter regions of integrin ITGA1, ITGA4, ITGA9, and nidogen NID1, NID2 genes in breast cancer." (PMID 33500458, 2021). "Direct bisulfite sequencing also showed widespread methylation occurring in intragenic regions of the WT1, PAX6 and ITGA4 genes and in the promoter region of the OTX2 gene in breast cancer tissues." (PMID 26121976, 2015).
gastric cancer (8 papers, 2007 to 2026). A primary or metastatic malignant neoplasm involving the stomach. "One limitation to the study may be that only the TIDE algorithm predicted a poor prognostic impact for CAF infiltration in COL1A1, COL5A1, ITGA4, EMILIN1, and TSPAN9 multivariate Cox model in gastric cancer." (PMID 35739492, 2022). "The opposite effect of this dual gene signature in adrenocortical carcinoma, kidney renal papillary cell carcinoma, and mesothelioma led us to identify ITGA4, EMILIN11, and TSPAN9 as interactors that potentiate the poor prognostic effect of CAFs specifically in gastric cancer." (PMID 35739492, 2022). "Therefore, we tested whether the addition of TSPAN9 to the CO1A1, COL5A1, ITGA4, and EMILIN1 Cox model can decrease the poor prognostic impact of CAF infiltration in gastric cancer." (PMID 35739492, 2022).
asthma (7 papers, 2006 to 2024). "As a proof-of-concept, sEVs from serum samples of T2high asthma patients tend to present higher levels of TH2-related proteins (ITGA4 and ITGB2) than the T2low counterparts, as expected." (PMID 39409176, 2024). "A “proof-of-concept” assay was also performed, with TH2 biomarkers ITGA4 and ITGB2 displaying a differential abundance in sEVs from T2high and T2low asthma patients." (PMID 39409176, 2024). "The expression levels of ITGA4 and ITGB2 in IL‐5‐activated eosinophils and that of CCR3 in IL‐5‐ or IL‐17‐activated eosinophils were significantly higher for patients with asthma than for normal individuals." (PMID 39575691, 2024).
COVID-19 (7 papers, 2021 to 2024). A disease caused by infection with severe acute respiratory syndrome coronavirus 2. "Nevertheless, the ITGA4 that was attributed to the “mildly activated” neutrophils was also reduced and clustered together with MHC class II genes in both KD and severe COVID-19 patients." (PMID 36159873, 2022). "Marker genes attributed to the “mild mature activated” neutrophil subset, such as ITGA4 or SLC38A1, were indeed elevated as well in the mild COVID-19 patients’ granulocytes of this study." (PMID 33441124, 2021).
colorectal cancer (6 papers, 2011 to 2025). A primary or metastatic malignant neoplasm that affects the colon or rectum. "For example, ITGA4 overexpression in chronic lymphocytic leukemia (CLL) correlates with disease progression and high-risk biomarkers, while its low expression in colorectal cancer is linked to poor prognosis." (PMID 40012546, 2025).
experimental autoimmune encephalomyelitis (6 papers, 2018 to 2021). An autoimmune demyelinating disease of the central nervous system that is produced experimentally in animals by the injection of homogenized brain or spinal cord in Freund's adjuvant. "Importantly, reduction of Itga4 by HDO ameliorates symptoms in both adoptive transfer and active experimental autoimmune encephalomyelitis models." (PMID 34937876, 2021).
inflammatory bowel disease (6 papers, 2015 to 2025). A spectrum of small and large bowel inflammatory diseases of unknown etiology. "ITGA4 (integrin subunit alpha 4) and monocyte percentage: ITGA4 has been recently associated with inflammatory bowel disease." (PMID 36782330, 2023). "Supporting this hypothesis, a prior genome-wide association study identified associations between inflammatory bowel disease susceptibility and increased immune activation of specific integrin genes (ITGA4, ITGB8, ITGAL, and ICAM1)." (PMID 39982236, 2025). "ITGA4 is targeted in therapies for multiple sclerosis (MS), Crohn’s disease, and inflammatory bowel disease (IBD)." (PMID 40012546, 2025).
Stroke (6 papers, 2014 to 2023). Sudden impairment of blood flow to a part of the brain due to occlusion or rupture of an artery to the brain. "A similar integrin molecule (ITGA4) was found to be upregulated in the peri-infarct area of rat brains after stroke and that its inhibition can reduce ischemic brain injury." (PMID 37468969, 2023). "Indeed, overexpression of ITGA4 in MSCs was found to enhance transendothelial migration in vitro, although a similar effect could not be reproduced in an in vivo rat model of stroke." (PMID 36273220, 2022).
glioblastoma (5 papers, 2009 to 2024). The most malignant astrocytic tumor (WHO grade IV). "Similarly, integrins CD49a (ITGA1), CD49d (ITGA4), CD51 (ITGAV), and CD11a (ITGAL) were selected for further validation based on elevated gene expression in glioblastoma-infiltrating T cells." (PMID 35464424, 2022).
neuroblastoma (5 papers, 2013 to 2022). Neuroblastoma (NB) is the most common solid, extracranial childhood tumor. "The role of RNF11 in the TGFβ pathway is of particular interest in neuroblastoma given our previous finding that the miR-17∼92 cluster components target TGFBR2 and SMAD2 as well as TGFβ downstream regulated genes CDKN1A, ITGA4, and SERPINE1." (PMID 23308108, 2013).
Obesity (5 papers, 2018 to 2024). Accumulation of substantial excess body fat. "ITGA4 was also related to allergic rhinitis associated with obesity, potentially due to its relevance on the leptin–osteopontin interaction in TH2 cells." (PMID 39409176, 2024). "To assess the hypothesis that UCP1 gene expression is inhibited by inflammation in obesity, we measured ITGA4 gene expression before and after the intervention." (PMID 30618796, 2018). "Our findings are in agreement with this, as scWAT ITGA4 mRNA expression decreased and UCP1 expression increased in the entire sample and in all BMI groups, particularly in the obesity group." (PMID 30618796, 2018). "Although the mechanisms by which obesity inhibits UCP1 expression remain unclear, a role of inflammation has recently been proposed, since integrin alpha 4 (ITGA4)- and VCAM-1 mediated macrophage-adipocyte interactions were found to inhibit UCP1 expression by ERK1/2 and p38 pathway blockade." (PMID 30618796, 2018).
ovarian carcinoma (5 papers, 2012 to 2024). A malignant neoplasm originating from the surface ovarian epithelium. "Meanwhile, higher mRNA expression of ITGA3 and ITGB4/8 were significantly associated with poor PFS, lower mRNA expression of ITGA4/A6/A7/A10/AX and ITGB1 were significantly associated with poor PFS in ovarian cancer patients." (PMID 32765584, 2020).
lymphoma (4 papers, 2014 to 2025). A malignant (clonal) proliferation of B- lymphocytes or T- lymphocytes which involves the lymph nodes, bone marrow and/or extranodal sites. "In this paper, we report the cytolytic activity of mAb ANAP against malignant lymphomas, which has not yet been observed with other ITGA4 antibodies." (PMID 41469420, 2025).
viral infection (4 papers, 2008 to 2024). "To assess the role of Itga4 deficiency in CD4 T cells during acute viral infection, we adoptively transferred SMARTA CD4 T cells, either transfected with crItga4 C+D or control crCd8, into WT B6 recipient mice." (PMID 39720725, 2024). "In the current study, we investigated the role of Integrin α4/CD49d, encoded by Itga4, in regulating the balance between TFH and TH1 cell populations during acute viral infection." (PMID 39720725, 2024). "We then examined the effects of Itga4 deficiency on TFH and TH1 cell differentiation during acute virus infection." (PMID 39720725, 2024).
cervical cancer (3 papers, 2014 to 2023). A primary or metastatic malignant neoplasm involving the cervix. "The methylation positive rates of RXFP3 and ITGA4 in cervical cancer were significantly higher than those in CIN1." (PMID 36803573, 2023). "The aim was to investigate the diagnostic value provided by methylation biomarkers of six tumor suppressor genes (ASTN1, DLX1, ITGA4, RXFP3, SOX17 and ZNF671) for cervical precancerous lesions and cervical cancer." (PMID 36803573, 2023). "In previous studies we have shown that hypermethylation of CpG islands in proximity to the genes DLX1, ITGA4, RXFP3, SOX17, and ZNF671 correlated with the presence of cervical precancerous lesions and cervical cancer." (PMID 30509219, 2018). "A methylation signature comprising the 5′ regions of the genes DLX1, ITGA4, RXFP3, SOX17 and ZNF671 specific for CIN3 and cervical cancer (termed CIN3+) was identified and validated." (PMID 24647315, 2014). "In cervical cancer a DNA hypermethylation marker panel consisting of the six marker regions ASTN1, DLX1, ITGA4, RXFP3, SOX17, and ZNF671 may be a useful tool for triaging HPV-positive women." (PMID 30509219, 2018). "DNA isolated from 49 tissue samples with no histological evidence for CIN (normal), from 43 samples diagnosed as CIN3 and from 54 cervical cancer tissues was bisulfite-treated and used in qMSP experiments for the five marker regions DLX1, ITGA4, RXFP3, SOX17, and ZNF671." (PMID 24647315, 2014).
ischemic stroke (3 papers, 2022 to 2025). A stroke disorder caused by obstruction of blood flow to the brain, due to thrombotic (local blood clot formation) or embolic (due to a blood clot or other material traveling from another site) event. "However, how candesartan regulates FFAR1/ITGA4 axis in the treatment of ischemic stroke needs further investigations." (PMID 36117589, 2022). "Interestingly, most of the top 10 upregulated DEGs, such as Thbs1, CD36, ITGA4, and ADAMTS12, are involved in the function of endothelial cells, as shown in the heatmap, implying a role of NeuroD1 in regulating the gene expression of endothelial cells post ischemic stroke." (PMID 38270116, 2023).
liver cancer (3 papers, 2017 to 2024). An epithelial or non-epithelial malignant neoplasm that arises from the liver. "In the comparison between the liver cancer and the other cancer groups, cDMCs (FDR < 0.0001) were detected at the promoters of the SPARC, NEUROG1, SH3GL3, and ITGA4 genes." (PMID 28751909, 2017). "Additionally, high‐dose BBR regulated the interactions from liver cancer immune cells to CD8+ T cells via ligand‐receptor pairs such as CCL3–CCR5, CCL5–CCR5, CXCL6–CXCR6, and SPP1–(ITGA4+ITGB1)." (PMID 39135526, 2024).
lung carcinoma (3 papers, 2007 to 2024). "We identified 7 DMRs corresponding to 7 differentially methylated genes (DMGs) including HOXB4, HOXA7, HOXD8, ITGA4, ZNF808, PTGER4, and B3GNTL1 that were highly associated with lung cancer by comparing the methylation profiles of lung cancer and benign nodule tissue." (PMID 37101220, 2023). "It turned out that the expressions of B3GNTL1 and HOXD8 were significantly upregulated, while the expression of remaining five genes (HOXB4, ZNF808, ITGA4, PTGER4, and HOXA7) were significantly downregulated in lung cancer tissues (p < 0.01)." (PMID 37101220, 2023).
Lymphadenopathy (3 papers, 2016 to 2020). Enlargement (swelling) of a lymph node. "Lymphadenopathy was detected in 72.8% of CLL patients and observed more in the high ITGA4 expression subset of CLL patients with p = 0.026." (PMID 32802392, 2020).
metastatic disease (3 papers, 2018 to 2023). "In terms of metastatic disease there was variable level of association seen in the CMI values with a significant association seen only in the ITGA4 and SDC2 individual genes." (PMID 37264006, 2023).
adenoma (2 papers, 2021). A neoplasm arising from the epithelium. "In contrast to FIT, methylated ITGA4 is derived from exfoliated cells, and DNA methylation signatures are considered to maintain during colorectal carcinogenesis from adenoma to cancer, which may help to explain the significantly higher sensitivity than FIT for AA and stage I patients." (PMID 34689777, 2021). "One study identified in the present systematic review found this marker to have 80% sensitivity and 100% specificity for CRC in stool, and methylated ITGA4 was found in 89% of CRC tissue samples and 88% of adenoma tissue samples." (PMID 33030559, 2021).
atherosclerosis (2 papers, 2022). A disease characterized by the build-up of fatty material and calcium deposition in the arterial wall resulting in partial or complete occlusion of the arterial lumen. "Each gene was expressed in both cell types with SVEP1 and ITGA4 more highly expressed in VSMCs and ITGA9 expression higher in endothelial cells, in keeping with the previous atherosclerosis studies." (PMID 35802072, 2022).
celiac disease (2 papers, 2011 to 2021). An autoimmune genetic disorder with an unknown pattern of inheritance that primarily affects the digestive tract. "As regards coeliac disease diagnosis above 7 years of age in the case–control analysis, rs653178 (at SH2B3/ATXN2), rs13010713 (at ITGA4/UBE2E3), rs13151961 (at IL2/IL21), rs11712165 (at CD80) and rs10936599 (at MYNN) showed an association." (PMID 33446885, 2021).
cholangiocarcinoma (2 papers, 2018 to 2022). A carcinoma that arises from the intrahepatic biliary tree (intrahepatic cholangiocarcinoma) or from the junction, or adjacent to the junction, of the right and left hepatic ducts (hilar cholangiocarcinoma). "For example, cholangiocarcinoma (CHOL) overexpresses a large variety of subunits (e.g. ITGAV, ITGA1, ITGA4, ITGA5, ITGA11, ITGB1, ITGB2, ITGB6), whereas, the equally deadly pancreatic adenocarcinoma (PAAD) overexpresses a very limited set of integrins, including ITGA6 and ITGB4." (PMID 30046394, 2018).
Cirrhosis (2 papers, 2019 to 2025). A chronic disorder of the liver in which liver tissue becomes scarred and is partially replaced by regenerative nodules and fibrotic tissue resulting in loss of liver function. "ITGA4 is primarily associated with cellular proliferation, migration, invasion, and the progression to cirrhosis and hepatocellular carcinoma." (PMID 40103586, 2025). "Our gene expression microarray data show that liver MSCs obtained from the liver of patients with fibrosis and cirrhosis express medium levels of VLA-1 (CD49a; ITGA1) and low levels of VLA-4 (CD49d; ITGA4)." (PMID 31546729, 2019).
colitis (2 papers, 2016 to 2018). Inflammation of the colon. "Previous studies have demonstrated that ITGA4 is hypermethylated in inflamed colon tissue/colitis, and that the treatment of anti-ITGA4 antibodies further aggravate colitis by IL-1β, TNF-α, and IFN-γ recruitment." (PMID 27111221, 2016). "Conversely, the treatment of ITGA4 antibodies in combination with conventional therapies alleviated colitis by suppression of IL-1β and iNOS in mouse models." (PMID 27111221, 2016).
colon cancer (2 papers, 2017 to 2021). "The ITGA4 gene encodes a membrane protein (integrin alpha 4) and is considered a risk marker for inflammation-associated colon cancer." (PMID 33030559, 2021).
colorectal adenoma (2 papers, 2017 to 2021). An adenoma that arises from the colon or rectum. "In addition, it was reported that the sensitivity of the combined study using three methylation markers of ITGA4, SFRP2 and p16 in stool samples for colorectal adenoma detection was 72.0% at 96.8% specificity." (PMID 33391430, 2021).
dermatitis (2 papers, 2022 to 2024). An inflammatory process affecting the skin. "ITGA4 was upregulated in the non-lesional epidermis from horses suffering from insect bite hypersensitivity, an IgE-mediated dermatitis caused by insect bites and has common features with human and canine AD92." (PMID 36482174, 2022).
fibrosis (2 papers, 2019 to 2025). the formation of excess fibrous connective tissue in an organ or tissue in a reparative or reactive process. "This suggests that PAE inhibits hepatic fibrosis through the ITGA4/FAK/PI3K/AKT signaling pathway, independent of the TGFβ-mediated pathway." (PMID 40103586, 2025).
graft versus host disease (2 papers, 2021 to 2024). An immune system disorder that occurs after allogeneic hematopoietic stem cell transplant and is a reaction of donor immune cells against host tissues. "In addition to skin trafficking molecules, they expressed ITGA4 and ITGB7, encoding the integrin α4β7 which facilitates entry to the intestine, and were localised in gastrointestinal graft versus host disease (GVHD) lesions." (PMID 38817613, 2024).
liver disease (2 papers, 2024 to 2025). "To test if this mechanism is relevant in human disease, we analyzed integrin expression (ITGA4, ITGAX) in human blood monocytes from patients with liver disease obtained from KUMC Liver Bank." (PMID 38704651, 2024). "The relationship between ITGA4 and PAE might also pertain to other liver diseases, necessitating further exploration." (PMID 40103586, 2025).
Oral Squamous Cell Carcinoma (2 papers, 2020 to 2022). "Previous reports indicate ITGA4 as a promising marker for oral squamous cell carcinoma and especially tongue oral cancer." (PMID 32937734, 2020). "Similarly, ITGA4 has been shown to correlate with prognosis in patients with early Oral Squamous Cell Carcinoma." (PMID 35681175, 2022).
osteoarthritis (2 papers, 2018). A noninflammatory degenerative joint disease occurring chiefly in older persons, characterized by degeneration of the articular cartilage, hypertrophy of bone at the margins and changes in the synovial membrane. "It was reported that the expression of integrin was associated with the osteoarthritis severity, especially ITGA4 (integrinα4)." (PMID 29317700, 2018).
periodontitis (2 papers, 2023 to 2024). An acute or chronic inflammatory process that affects the tissues that surround and support the teeth. "ITGs, which mediate cell-matrix interactions and leukocyte migration and adhesion, were consistently overexpressed in T2DM-related periodontitis, and the ITGA4 upregulation was confirmed at the protein level." (PMID 38241313, 2024). "In the Pg sample, we observed interactions between ADM and CALCRL, which is related to periodontitis; EDA and EDA2R, which is related to ectodermal development; and SPP1 and CD44 and SPP1 and (ITGA4+ITGB1), which promotes phosphoprotein secretion and regulates bone salinization." (PMID 37287452, 2023).